TNF (tumor necrosis factor)
Diseases named in the same sentence as TNF in open-access papers (continued):
Sharing a sentence is not in itself a finding about the gene and the disease.
infection (continued). "One of these cytokines is TNF-alpha, which appears to be important for infection control and progression of M. tuberculosis in humans, and likewise in zebrafish, TNF-alpha can promote the bactericidal effects of macrophages." (PMID 41011808, 2025). "When the body receives a stimulus or infection, substances such as TNF and IL-1 reach the brain and promote NREM sleep." (PMID 39940855, 2025). "As infection progresses, excess tumor necrosis factor (TNF) was seen in the zebrafish models to stimulate ROS production and activate Cyclophilin D, a mitochondrial permeability transition pore regulator, triggering programmed necrosis of infected macrophages." (PMID 41009463, 2025). "Stimulation of piglets with weaning stress or pathogen infection leads to increased expression and secretion of pro-inflammatory factors IL-6, TNF-α and IL-1β." (PMID 40351768, 2025). "Despite comparable bacterial loads early in infection, granulomas in membrane TNF mice exhibit abnormal organization and reduced numbers during chronic stages." (PMID 40427602, 2025). "TNF-α, IL-1β, and IL-8 mRNA expression were significantly increased in the intestine after infection with A. hydrophila from grass carp." (PMID 40137743, 2025). "The immune system promptly releases TNF‐α to initiate inflammation when the organism encounters an infection, sustains an injury, or is otherwise stimulated." (PMID 41256228, 2025). "In terms of infection risks, a study on systemic therapies for PsO revealed that cutaneous bacterial infections were frequently observed in patients receiving TNF-α and IL-17 inhibitor treatments." (PMID 40408459, 2025). "Infection with the wild-type strain led to increases in the levels of the inflammatory cytokines IL-6, TNF-α, and IL-10, but deletion of the porV locus significantly reduced the levels of these factors (P ≤ 0.01)." (PMID 40484959, 2025). "It produces low-endotoxic LPS to evade detection via TLR4, and suppresses TNF-α production in early infection stages." (PMID 40943382, 2025). "Sequential infections revealed that prior RSV infection decreased TNF-α and IL-6 levels following subsequent IAV infection, suggesting protective effects mediated by innate immune responses." (PMID 40005506, 2025). "Although M. abscessus can induce the production of pro-inflammatory cytokines such as TNF-α and IL-6, the inflammatory response can be regulated to prevent pathogen elimination and, in some cases, promote infection persistence." (PMID 40005812, 2025). "After infection of mice with the HY/HA-ΔL226/R229I strain, levels of TNF-α decreased at 3 dpi, while IL-6 and IL-1β levels increased at 5 dpi." (PMID 40338080, 2025). "In this study, we systematically evaluated the changes in the expression levels of immune-related genes IgT, IgM, and TNF-α in grass carp after infection with I. multifiliis." (PMID 40284708, 2025). "TNF-alpha and IL-6 are pivotal in mediating the body’s response to injury and infection and play complex roles in neural plasticity, brain function, and the pathophysiology of neurodegenerative diseases." (PMID 39906616, 2025). "After the infection, RNA was extracted and reverse transcribed, and the transcription of pro-inflammatory factors IL-6, IL-8, and Tumor Necrosis Factor-α (TNF-α) was detected with reverse transcript polymerase chain reaction (RT-PCR)." (PMID 40332097, 2025). "Differentiation of the CD14+ peripheral blood monocytes to macrophages using M-CSF and GM-CSF reduced the influence of TcpC on IL-1β- and TNFα-secretion during an infection with CFT073." (PMID 41310197, 2025). "Our vaccination protocols that resulted in significant protection against infection induced the expression of multiple cytokines including IL-6, IFN-γ, TNF and IL-17, which have been associated with a more effective control of T. cruzi infection." (PMID 41181325, 2025).
infection (continued). "When the piglets were administered levamisole or baicalin, the mRNA expression levels of IL-1β, IL-18, and TNF-α in the blood vessels were weakened compared to the infection group (p < 0.001)." (PMID 40427615, 2025). "This preceded the transcriptional upregulation of inflammatory cytokines, including IL-1β, IL-6, IL-18, and TNF-α, which only became prominent at 12-24 hours post-infection." (PMID 41281739, 2025). "Here, we found that 10 mM of L-serine significantly reduced the expression of inflammatory cytokines (mainly IL-1β and TNF-α) in P. multocida—infected macrophages (the most significant changes were at 12 h post infection)." (PMID 40267013, 2025). "KEGG pathway analysis further highlighted inflammation/infection-related pathways (e.g., “Cytokine-cytokine receptor interaction”, “TNF signaling”, and “Toll-like/NOD-like receptor signaling”) and cancer-associated pathways." (PMID 41039310, 2025). "Offspring of HFD-fed dams exhibited significantly blunted cytokine and chemokine responses during infection, including reduced levels of serum GM-CSF, TNF-α, IL-1β, IL-6, IL-10, and MCP-1 and peritoneal G-CSF, IL-6, and MCP-1." (PMID 40766470, 2025). "Compared to the GPS infection group, the expression of IL-6 in the 25 μg/mL baicalin group was significantly lower (p < 0.05), while the expressions of IL-1β and TNF-α were insignificantly lower (p > 0.05)." (PMID 40867785, 2025). "Infection with Mtb triggers in resister AM a higher production of TNF and significantly stronger TNF signaling relative to LTBI AM." (PMID 39836471, 2025). "After the challenge, a shift in the correlation profile was observed, with a significant positive correlation between the TNFα and IL1β, indicating the potential modulation of the immune response during infection." (PMID 41150396, 2025). "When the cells were treated at the time of infection, TNF-α expression was 0.104 (±0.010)-fold lower at 1 mM BA and 0.230 (±0.047)-fold lower at 10 mM BA." (PMID 41373953, 2025). "By day 5 post infection, TNF stimulation significantly increased LPO accumulation only in the B6.Sst1S macrophages." (PMID 41037321, 2025). "Consistent with prior reports we observed that bone marrow-derived macrophages (BMDMs) infected with L. interrogans serovar Copenhageni strain Fiocruz L1-130 at a multiplicity of infection (MOI) of 100 elicited the secretion of TNF, IL-10, and IL-6." (PMID 40501870, 2025). "During infection, the early viral protein E1A sensitizes cells to TNFα-induced apoptosis, which is subsequently counteracted by the E1B-19K protein." (PMID 40103806, 2025). "M1 macrophages are activated during the acute infection phase, releasing cytokines like TNF‐α, IL‐6, and IL‐1β to control infection." (PMID 40060195, 2025). "The present study using the murine HoxB8 model showed that the wild-type W83 strain upregulates TNF-α release in an MOI-dependent manner after 24 h of infection." (PMID 39936030, 2025). "The top 10 most significantly enriched KEGG pathways included TNF signaling and various infection-related pathways." (PMID 40568695, 2025). "For the exogenous apoptosis inducing molecules, the expression of FasL was upregulated more significant than Trail and TNF-α, as infection increasing." (PMID 40038739, 2025). "In fact, inhibition of ADA by EHNA after 3 h of infection with TcdA in the ileum of mice reduces tissue damage, neutrophil infiltration, and the level of the pro-inflammatory cytokines TNF-α, IL-1β, as well as the expression of NOS2, NF-κB and PTX3." (PMID 40646589, 2025). "In control macrophages, both HN878 and CDC1551 infections significantly increased the levels of proinflammatory (TNFα, IL1β, IL6, and CXCL8) and anti‐inflammatory (IL4 and IL10) molecules and GMCSF." (PMID 41287823, 2025). "Pathogen infection or viral proteins induce the release of inflammatory cytokines such as IL-6 and TNF-α, which subsequently suppress key antioxidant proteins like GPX4 and SLC7A11, initiating ferroptosis." (PMID 41479924, 2025).
infection (continued). "For example, ILC1s can be activated and secrete IFN-γ and TNF-α after infection with the H1N1 influenza virus as early as three days after infection." (PMID 39861052, 2025). "Although guidelines generally recommend screening for tuberculosis infection before initiating TNF-α inhibitor therapy, TNF-α inhibitors can not only reactivate latent tuberculosis but also increase susceptibility to new infections." (PMID 40763141, 2025). "ELISA results indicated that the cytokine levels of IL-1β, IL-6, and TNF-α in the serum of mice remained relatively stable at 6 h post-infection." (PMID 40170927, 2025). "To assess this, we measured levels of the pro‐inflammatory cytokines TNF‐α and IL‐6 at 24 h post‐infection." (PMID 40574345, 2025). "The characteristic gene expression of dormant infection suggested the activation of interleukin (IL)-17 and tumor necrosis factor (TNF) pathways that drive synovial CXCL5 expression, which should stimulate neutrophil recruitment." (PMID 41387890, 2025). "We observed a robust cytokine response, including TNF-α, IL-6, G-CSF, and IL-1RA, peaking 6 h post-infection." (PMID 40766078, 2025). "The production of proinflammatory cytokines, particularly TNF-α, plays a fundamental role in controlling parasite proliferation during the early stages of infection." (PMID 41011132, 2025). "Tubastatin A, an HDAC6 inhibitor, has been shown to enhance the immune response to M. tuberculosis by decreasing IL-10 levels and increasing TNF-α levels, and increasing the influx of immune cells to the site of infection." (PMID 40141021, 2025). "Mice infected with the nonlethal P. yoelii strain (Py17X) start producing TGF-β five days after infection, which aligns with a drop in parasitemia and a decrease in TNF-α levels, ultimately leading to recovery." (PMID 39907835, 2025). "Consistent with a shift toward a more activated phenotype upon infection, an increase in TNF and complement signaling between neutrophils and several immune and non-immune cell types was observed, most notably with monocyte/macrophages." (PMID 40704794, 2025). "In the in vivo experiments, the ΔclpB infection group had faster wound healing, reduced tissue damage, and decreased expressions of TNF-α and IL-6 at both protein and mRNA levels." (PMID 41425934, 2025). "TNF-α is also one of the main mediators of systemic inflammation, which in turn also plays an important role in the immune response to various infections." (PMID 40141021, 2025). "In response to in vitro infection, monocytes secrete type I interferons (IFNs), tumor necrosis factor-α (TNF-α), granulocyte colony-stimulating factor (G-CSF), and IL-6, enabling the activation and recruitment of innate and adaptive immune cells." (PMID 41280933, 2025). "In this model, TNF-α signaling was the most important upstream master regulator, because its blockade completely protected mice from lethal infection and suppressed the induction of most cytokines such as IL-1β, IL-17A, IL-6, and IL-12p70." (PMID 40127923, 2025). "IFN-γ activates macrophages, enhancing their bactericidal capacity, while TNF-α contributes to granuloma formation, which aims to contain the infection." (PMID 40005812, 2025). "The increased levels of TNF-α, IL-1β, and IL-6 promote endothelial activation and leukocyte recruitment to the site of infection, which plays a crucial role in the host’s innate immune defense." (PMID 40564979, 2025). "Knocking-down FTO hindered the infection-induced decrease in m6A modification levels of TNF-α transcripts, accompanied by a dampened immune response and uncontrolled T. gondii proliferation." (PMID 40663568, 2025). "Most of these genes are also upregulated at 48 hours post-infection, and an additional 2418 genes were upregulated, including finTRIM82 and tumour necrosis factor alpha (TNFα)." (PMID 41181121, 2025).
infection (continued). "The acute phase response is activated by the release of inflammatory cytokines, especially interleukin (IL)-1, IL-6, and tumor necrosis factor (TNF)-α from the macrophages or blood monocytes at the site of inflammatory lesions or infections." (PMID 39858163, 2025). "Concurrently, gaseous irritants such as NO2 and O3 disrupt epithelial barrier integrity and trigger excessive release of pro-inflammatory cytokines (e.g. IL-6, TNF-α), priming the lungs for exaggerated inflammatory responses upon infection." (PMID 40688748, 2025). "The qPCR analysis revealed significant upregulation of IL-6, IL-17A, IL-22, IFN-β, IFN-γ, and TNF-α in duodenal epithelial cells following IBV CSL strain infection." (PMID 40871421, 2025). "Infection with P. aeruginosa can not only increase the levels of the proinflammatory cytokines IL-1β, IL-6, and TNF-α but also reduce the expression of the inhibitory cytokine IL-10." (PMID 40270824, 2025). "The authors concluded that TNF-alpha inhibitor use before spinal surgery led to significantly higher reoperation rates due to infection or mechanical failure." (PMID 41306173, 2025). "TNF-α (Tumor Necrosis Factor-alpha) Is a potent pro-inflammatory cytokine that Induces fever, Increases vascular permeability, and promotes Immune cell recruitment to sites of Infection." (PMID 40951884, 2025). "C57BL/6 mice are more resistant to this infection than BALB/c and IL-4-deficient (IL4−/−) C57BL/6 mice exhibited increased parasite burdens, heightened IFN-γ and TNF-α production, and a shift from IgG1 to IgG2a antibodies." (PMID 40725240, 2025). "Some reports have found a higher frequency of triple-producing CD4+ T cells (IFN-γ, IL - 2, and TNF-α) in patients with active TB disease in comparison to patients with latent TB-infection." (PMID 40990013, 2025). "At 48 h post-infection, the TNF and insulin signaling pathways remain continuously activated, and autophagy and ferroptosis, a novel cell death mode, are observed." (PMID 40872699, 2025). "The infection caused a robust but controlled immune response with elevated levels of MCP-1, TNF-α, and IL-6, that prevented severe neuronal damage." (PMID 41474758, 2025). "HCV antigen–stimulated CD4+ T cells produced IL-21, IFN-γ, and TNF at the week 8 or 11 peak and at lower frequencies at week 20 or 24 after infection." (PMID 40956619, 2025). "In subtype C, we found that the changes in the biomarker profiles post infection compared to pre-infection were due to increases in TNFα, IL-10, IL-6, IL-13, IL-5, IFNγ, IL-12, IL-4, ITAC, IL-17α, and IL-23." (PMID 40862133, 2025). "TNFα is a central inflammatory mediator with pleiotropic functions that is expressed by macrophages in the early phase of an infection." (PMID 40517265, 2025). "The primary function of TNF is to activate and recruit additional immune cells to the site of infection." (PMID 41003928, 2025). "At 96 h post-infection, the percentage of TNF-α-positive macrophages (12.7%) in PRV-infected mice with NSA treatment was markedly lower than that in PRV-infected mice without NSA treatment (32.8%)." (PMID 40704967, 2025). "SOR pretreatment also resulted in reduced levels of the inflammatory markers IL-6 and TNF-α in the BALF at 6 days post infection." (PMID 40858544, 2025). "The human body initiates an inflammatory response in reaction to injury or infection, which triggers the production of IL-1, IL-6, IL-8, TNF-α, and other inflammatory factors by white blood cells." (PMID 41142623, 2025). "The infection triggers a systemic inflammatory response, including elevated IL-6, TNF-α, and IL-1β, which amplifies vascular injury." (PMID 41012624, 2025). "Other cytokines assayed had weak correlation with atRA due to distinctly different cytokine levels in either Asp (IL‐21, IL‐22) or MRSA (TNFα) infection." (PMID 40031928, 2025).
infection (continued). "Mean concentration values [pg/mL] ± standard deviation of selected proinflammatory cytokines: TNF-alpha, IL-1β and IL-6 in infections with atypical pathogens in patients with PCOS." (PMID 40647668, 2025). "IL-6 plays a crucial role in the progression of VL, exhibiting various effects, such as inducing immunosuppression in the liver of the infected host, increasing hypergammaglobulinemia, and inhibiting TNF-α production during the early stage of infection." (PMID 39670465, 2025). "For instance, TNF-α released by AlvMφ contribute to bronchiolar fibrosis in weanling rats upon infection." (PMID 39796262, 2025). "With the rising concern of nonarchetypal strains of T. gondii, at-risk populations such as older individuals and immunocompromised patients need updated guidelines for infection prevention when using anti-TNF-α therapy." (PMID 39959486, 2025). "During wound healing, M1 macrophages (pro-inflammatory) dominate the early phase, producing cytokines like TNF-α and IL-1β to combat infection and clear debris." (PMID 40894219, 2025). "A pronounced, infection-dependent increase in the expression levels of TNF, IL-8, and IL-10 was observed over the course of infection, with the most substantial upregulation occurring at the earliest time point." (PMID 40794782, 2025). "Upon infection with virulent M. tuberculosis, membrane TNF supports survival during acute phases, similar to wild-type mice, yet fails to prevent disease progression during chronic infection, leading to increased lung pathology and eventual mortality." (PMID 40427602, 2025). "TNF‐α, a pro‐inflammatory cytokine, attracts immune cells to areas of injury or infection and boosts them." (PMID 40625633, 2025). "Autophagy can be triggered by infections, cytokines (e.g., TNF, IFN-γ), and activation of pattern recognition receptors (PRRs), such as TLRs and NLRs." (PMID 40333197, 2025). "Mammalian glia produce pro-inflammatory cytokines, tumor necrosis factor alpha, interleukin-1β, and interferon-γ, to drive glial phagocytosis in response to injury or infection." (PMID 41325349, 2025). "Compared to the infected iPSCs, HLCs exhibit enriched genes for the TNFα signalling pathway via NF-kB upon pHV infection with insertions in the 5’UTR and for the androgen response pathway in introns." (PMID 40664913, 2025). "In response to the infection, immune cells produce pro-inflammatory cytokines such as interleukin (IL)-1, IL-6, and tumor necrosis factor (TNF)-α, which disrupt homeostasis." (PMID 39941433, 2025). "Regarding inflammatory response, the untreated group exhibited significantly elevated levels of pro-inflammatory cytokines TNF-α and IL-6, reflecting a strong infection-induced inflammatory response." (PMID 40149043, 2025). "At different time points post infection, the mRNA level of the cytokines TNF-α, IL-8, and IL-6 were monitored by RT-qPCR." (PMID 40253364, 2025). "Infections, especially chronic ones, are characterized by numerous complications resulting from interactions at the cellular level of both TNF-α, IL-6 and IL-8." (PMID 40647668, 2025). "Infection upregulates proinflammatory cytokines such as TNF-α and IFN-γ and chemokines such as CCL2/MCP-1, CCL3/MIP-1α, and CCL5/RANTES, while downregulating the astrocytic glutamate transporter, GLT-1." (PMID 40743275, 2025). "In order to further investigate TNFα-mediated NF-κB activation, we combined infection with TNFα treatment." (PMID 40103806, 2025). "The production of pro-inflammatory cytokines, IL-6, MCP-1, and TNF-α, was substantially elevated at 3 or 7 dpi in the infection control group relative to the treatment groups." (PMID 41165324, 2025). "Severe infection and clozapine itself can lead to alterations in interleukin-6, interleukin-1, interferon-ɣ and tumor necrosis factor-α leading to decreases in CYP1A2 and the body’s capacity to metabolize clozapine." (PMID 40704031, 2025).